YTHDF1 (YTH N6-methyladenosine RNA binding protein F1)
Diseases named in the same sentence as YTHDF1 in open-access papers (continued):
Sharing a sentence is not in itself a finding about the gene and the disease.
liver cancer (37 papers, 2020 to 2025). An epithelial or non-epithelial malignant neoplasm that arises from the liver. "By enhancing the translation of mRNA transcripts encoding immune-suppressive molecules, such as PD-L1, YTHDF1 facilitates immune escape by enabling liver cancer cells to evade immune detection and destruction." (PMID 39911396, 2025). "Research has demonstrated that YTHDF1, a key m6A reader protein, plays a significant role in regulating the immunogenicity of liver cancer cells through its modulation of various tumor-associated genes." (PMID 39911396, 2025). "YTHDF1 was upregulated in liver cancer and this upregulated expression was associated with cancer development and progression, and therefore it was recognized as an oncogene." (PMID 37833468, 2023). "Studies have shown that METL3 and YTHDF1 levels are higher in liver cancer and are associated with a poor OS rate." (PMID 34206803, 2021). "Many studies have reported upregulation of YTHDF1 in liver cancer tissues and its overexpression is associated with poor HCC prognosis." (PMID 34692544, 2021). "The analysis of The Cancer Genome Atlas (TCGA), Gene Expression Omnibus (GEO) databases and the immunohistochemical analysis have shown that YTHDF1 is upregulated, associated with poor overall survival (OS) and pathologic staging of liver cancer." (PMID 33692959, 2021). "Targeting YTHDF1 could increase the susceptibility of liver cancer to immune checkpoint blockade, thus improving survival outcomes for patients." (PMID 39911396, 2025). "In liver cancer, YTHDF1 recognizes m6A markers on SLC7A11 mRNA, intensifying ferroptosis inhibition, while in liver stellate cells, YTHDF1 identifies m6A markers on BECN1 mRNA, amplifying ferritin phagocytosis and triggering ferroptosis." (PMID 40327848, 2025). "Despite the emerging evidence highlighting the role of YTHDF1 in immune modulation and tumor progression, research on its precise mechanisms in liver cancer remains in the early stages." (PMID 39911396, 2025). "Nevertheless, additional studies are required to comprehensively uncover the molecular mechanisms through which YTHDF1 regulates translation and to better understand its broader impact on liver cancer biology." (PMID 39911396, 2025). "METTL3 can also catalyze YTHDF1 mediated m6A to increase Snail mRNA translation and epithelial-mesenchymal transition to induce liver cancer metastasis." (PMID 40097750, 2025). "YTHDF1, a central protein in HCC research, has been linked to poor patient outcomes due to its overexpression in liver cancer tissues." (PMID 38898486, 2024). "The translation of FZD5 mRNA was promoted by YTHDF1 in an m6A-dependent manner, which subsequently facilitated liver cancer progression." (PMID 39735608, 2024). "Our exploratory analyses using the TIMER database revealed a strong positive correlation between IFN-α/β receptor (IFNAR) and YTHDF1 in 4 cancer types including melanoma, glioma, prostate, and liver cancer (P < 0.001)." (PMID 39325547, 2024). "Combined upregulation of METTL3 and YTHDF1 was validated as a biological marker reflecting the malignancy level of liver cancer and patient prognosis." (PMID 38856795, 2024). "Unfortunately, this study was based only on clinical data, and no in vivo and in vitro experiments were performed for verification; thus, the role of YTHDF1 in liver cancer needs to be further explored." (PMID 35155557, 2022). "The knockdown of METTL3 or YTHDF1 attenuated Snail expression and suppressed liver cancer migration and invasion." (PMID 36009465, 2022). "YTHDF1 has also been confirmed to be abnormally expressed in liver cancer, and its expression is upregulated in tumor tissues." (PMID 35155557, 2022). "HCC is the most common type of liver cancer, and YTHDF1 expression was found to be largely upregulated in HCC in multiple patient cohort studies with positive correlation to pathological stage." (PMID 35884552, 2022).
liver cancer (continued). "Intriguingly, m6A enrichment in Snail CDS, but not 3′UTR, was associated with increased Snail mRNA translation, which was mediated by YTHDF1 in liver cancer." (PMID 36009465, 2022). "YTHDF1 expression is also significantly upregulated in liver cancer, and it is positively correlated with pathological stage." (PMID 34246319, 2021). "Some researchers have proposed that, as in liver cancer, new risk signatures constructed from 5 m6A-related genes (METTL3, METTL14, KIAA1429, ALKBH5 and YTHDF1) can be used as independent prognostic factors for PAAD." (PMID 34246319, 2021). "YTHDF1 is an independent adverse prognostic factor involved in regulating the cell cycle and metabolism of liver cancer." (PMID 33692959, 2021). "For example, in liver cancer, YTHDF1 mediates m6A-increased translation of Snail mRNA, and the methylation is catalyzed by METTL3, suggesting the acceleration mediated by METTL3/YTHDF1 complex for the methylated target mRNA30." (PMID 33099572, 2020). "Notably, YTHDF1 promotes liver cancer stemness maintenance coupled with tyrosine kinase inhibitors resistance (lenvatinib, sorafenib) within patient-derived organoid models." (PMID 40986143, 2025). "Here, we found that METTL3 was significantly positively correlated with YTHDF1 in liver cancer." (PMID 40097750, 2025). "Moreover, YTHDF1 was upregulated in liver cancer cells, and knockdown of YTHDF1 significantly inhibited the expression of BFSP1." (PMID 40097750, 2025). "Elevated expression of YTHDF1 in liver cancer cells inhibits immune cell activation and proliferation by regulating the translation of immune-related transcripts, ultimately fostering an immune-suppressive environment that allows tumor cells to escape immune surveillance." (PMID 39911396, 2025). "Additionally, METTL3 enhances the stability of BFSP1 mRNA in a YTHDF1 dependent manner, thereby promoting aerobic glycolysis in liver cancer cells." (PMID 40097750, 2025). "Notably, YTHDF1 has been shown to enhance liver cancer stem cell renewal and confer resistance to multiple tyrosine kinase inhibitors including lenvatinib and sorafenib in patient-derived organoid models." (PMID 40986143, 2025). "So it proves that YTHDF1 can serve as a potential molecular target for liver cancer treatment." (PMID 38166832, 2024). "Experiments in vitro and in vivo have demonstrated that YTHDF1 could promote liver cancer's proliferation and metastasis." (PMID 37170222, 2023). "In addition, the methylation recognition enzyme YTHDF1/2 has also received important attention in cancer, and studies have found that they affect the occurrence of liver cancer and leukemia by regulating AKT and TNFR." (PMID 35141221, 2022). "In liver cancer, high expression of METTL3 and YTHDF1 is associated with worse overall survival, which leads to elevated m6A levels of the Snail gene, a pivotal transcription factor for epithelial-to-mesenchymal transition (EMT), and increases Snail expression through YTHDF1-mediated translation." (PMID 33758623, 2021). "Therefore, we speculated that METTL3 may mediate the m6A modification of BFSP1 mRNA and affect aerobic glycolysis in liver cancer by enhancing the stability of BFSP1 mRNA in a YTHDF1 dependent manner." (PMID 40097750, 2025). "Moreover, upregulated METTL3 and YTHDF1 expression was found in liver cancer that could serve as adverse prognosis factors for patients." (PMID 36009465, 2022). "Here, we found that METTL3 induces aerobic glycolysis in liver cancer by upregulating m6A modification of BFSP1, which can be achieved by recruiting YTHDF1." (PMID 40097750, 2025).
liver cancer (continued). "We also constructed a score model including YTHDF1 and YTHDF2 in LIHC, and divided the liver cancer patients into a high-score group and a low-score group." (PMID 37833468, 2023). "In conjunction with METTL3-mediated m6A modification, YTHDF1 can directly induce the translation of Snail, a key transcription factor of EMT, thereby promoting liver cancer metastases." (PMID 35884552, 2022). "The results showed that overexpression of METTL3 and YTHDF1 promoted the ECAR levels and reduced the OCR levels in liver cancer cells, which could be reversed by knockdown of BFSP1." (PMID 40097750, 2025). "Taking YTHDF1 as an example, studies have found that knocking out YTHDF1 can significantly inhibit the proliferation, migration, and invasion of HCC cells, and enhance in vitro cell apoptosis based on liver cancer cases in TCGA." (PMID 38166832, 2024). "In liver cancer, circRHBDD1 can recruit YTHDF1 and combine with m6A modified PIK3R1 mRNA, improve the translation level of PIK3R1 mRNA, promote the glycolysis of liver cancer cells through subsequent PI3K/AKT signal transduction pathway and make liver cancer resistant to anti-PD-1 treatment." (PMID 37582735, 2023). "METTL3 affects FOXO3 RNA stability in a YTHDF1-dependent manner to inhibit the expression of FOXO3 to inhibit autophagy; The reduced expression of METTL3 increases the number of autophagosomes to activate autophagy in liver cancer cells." (PMID 35141221, 2022).
colon carcinoma (34 papers, 2019 to 2025). "Chen and collaborators (2021) recently reported that YTHDF1 is associated positively with cisplatin resistance in colon cancer." (PMID 35186927, 2022). "In colon cancer, Chen and collaborators demonstrated YTHDF1-mediated as a positive association between glutamine metabolism and cisplatin resistance." (PMID 35186927, 2022). "In a colon cancer tumor-bearing mouse model, YTHDF1-deficient mice show tumor growth inhibition and longer survival than control mice." (PMID 33777035, 2021). "YTHDF1 is overexpressed in human colon cancer tissues, and its expression is associated with a poor prognosis of colon cancer." (PMID 34721530, 2021). "Another m6A reader YTHDF1 was associated with various malignant tumor behaviors, such as depth, lymph node metastasis, and poorer cancer stages in colon cancer." (PMID 32993738, 2020). "In YTHDF1-deficient melanoma or colon cancer, antigen cross-presentation by tumor-infiltrating DCs induces a stronger anti-cancer immune response and mature YTHDF1-deficient DCs can activate T cells more effectively than wild-type cells, leading to stronger anti-tumor immunity." (PMID 39759516, 2024). "Additionally, oncoprotein c-Myc enhances YTHDF1 expression in colon cancer to induce cancer cell proliferation and resist fluorouracil and oxaliplatin, where YTHDF1 is associated with advanced cancer stages, metastasis, and prognosis." (PMID 37437245, 2023). "The antigen cross-presentation of tumor-infiltrating DCs in YTHDF1-deficient melanoma or colon cancers can induce stronger anticancer immune response, and both in vitro and in vivo, mature YTHDF1-deficient DCs can induce stronger T cell activation than wild-type cells." (PMID 34956201, 2021). "The initial investigation on the relevance of YTHDF1 in human colon cancer biopsies indicated that low levels of YTHDF1 correlated with high CTL abundance." (PMID 41176596, 2025). "According to a recent study on colon cancer, YTHDF1 can promote the translation of RELA, participate in the NF‐κB pathway, and promote tumor development." (PMID 39821576, 2025). "It has been found that YTHDF1 can promote glutaminase (GLS) protein synthesis in colon tumors and highly expressed YTHDF1 can lead to the development of drug resistance." (PMID 39033180, 2024). "Our data demonstrate that Ythdf1 deletion in DCs sensitized tumors to IR in murine colon cancer and melanoma." (PMID 39325547, 2024). "Whilst the read-outs of epitranscriptome marks such as m6A-methylation are very diverse, epitranscriptomic and mRNA translation control of GLS is supported by YTHDF1-dependent GLS regulation in colon cancer." (PMID 39313128, 2024). "YTHDF1 was highly expressed in cisplatin-resistant colon cancer cells and increased the translation of glutaminase 1 (GLS1) to enhance colon cancer cell proliferation." (PMID 36835633, 2023). "The inhibition of GLS1 leads to an increased sensitivity to cisplatin-induced cell death and YTHDF1 is also a potential target in overcoming resistant colon cancers." (PMID 37055798, 2023). "Mouse xenograft assays further demonstrate that YTHDF1-AFA mutants decreased the colon cancer mass and size via decreasing c-Myc expression." (PMID 37086786, 2023). "As readers of m6A, YTHDF1 has high expression in colon cancer, and knockdown of YTDHF1 expression significantly inhibits the CRC cells tumorigenicity in vitro, mouse xenograft tumors the growth and Wnt/β-catenin pathway activity in CRC cells." (PMID 37170222, 2023). "In melanoma and colon cancer models, YTHDF1 knockout mice showed favorable outcomes and increased CD8 positive T cells and NK cells." (PMID 36479088, 2022). "YTHDF1 is up-regulated in human colon cancer tissues, which predicts the poor prognosis of colon cancer patients." (PMID 33816306, 2021). "Further analysis indicated a strong positive correlation between IGF2BP1 and YTHDF1 in colon cancer." (PMID 33500720, 2021).
colon carcinoma (continued). "The expression of YTHDF1 was found to be induced by the oncogenic transcription factorc-MYC, and this axis c-MYC/YTHDF1 promotes colon cancer cell proliferation and induces the resistance against anticancer drugs." (PMID 32316617, 2020). "Another study found that YTHDF1 was involved in the regulation of long-term neoantigen-specific immunity, and YTHDF1-deficient mice had an increased antigen-specific CD8+ T-cell antitumor response in colon cancer." (PMID 36091006, 2022). "In colon cancer, knockout YTHDF-1 enhances PD-L1 immunotherapy." (PMID 33777035, 2021). "In addition, the detection of YTHDF-1 is used to evaluate the prognosis of patients with colon cancer." (PMID 33777035, 2021). "Overexpression of YTHDF1 can reduce the sensitivity of colon cancer cells to cisplatin." (PMID 34677810, 2021). "Then, we validated that YTHDF1 is overexpressed at the mRNA level in 30 primary CRC tissue compared with adjacent normal tissue To further validate the expression level of YTHDF1, we detected the expression of YTHDF1 protein in 15 colon cancers and adjacent tissues by immunohistochemistry (IHC)." (PMID 31131257, 2019). "IR resulted in a pronounced inhibition of tumor growth in Ythdf1-cKO mice compared with WT mice, as assessed by both tumor volume and animal survival, in both MC38 colon carcinoma and B16-SIINFEKL(OT-I)-Zsgreen (B16-OZ) melanoma models." (PMID 39325547, 2024). "Compared to normal colon tissues, a great number of m6A regulators with CNV deletions had lower expression in colon cancer tissues (for instance, ALKBH5), and vice versa (e.g., YTHDF1, IGF2BP2, HNRNPA2B1, etc.)." (PMID 36119534, 2022). "First, we divided 566 colon cancer samples from GSE39582 into two clusters in the same way as performed in TCGA and found the distribution of ALKBH5 and YTHDF1 expression in the two clusters to be quite similar to that in TCGA." (PMID 34079761, 2021). "It is reported that YTHDF1 and HNRNPC can be used as prognostic factors for colon cancer and have potential value for colon cancer treatment." (PMID 32974160, 2020). "The m6A reader YTHDF1 targets the putative binding motif in the 3’ UTR of GLS1 to boost the function of GLS1, facilitate glutamine metabolism and contribute to the progression of cisplatin-resistant colon cancer." (PMID 37055798, 2023). "At present, only METTL3, YTHDF1, YTHDF3 was researched in colon cancer, other roles of m6A enzymes remain unclear." (PMID 32993738, 2020).
melanoma (34 papers, 2020 to 2025). A malignant, usually aggressive tumor composed of atypical, neoplastic melanocytes. "Recent studies have shown that YTHDF1 is highly expressed and associated with poor prognosis in various tumor tissues such as colon cancer, melanoma, liver cancer, and non-small cell lung cancer." (PMID 35197112, 2022). "In a melanoma model in mice, YTHDF1-deficient mice showed slower tumor growth and longer survival than wild-type mice." (PMID 33777035, 2021). "In addition, the growth speed of YTHDF1-deficient melanoma cells was lower than that of wild type (WT) cells in mice." (PMID 37124930, 2023). "The inhibitory factor HINT2 mRNA translation is stimulated by YTHDF1 in melanoma, and its absence enhances the anti-melanoma immune response." (PMID 38339157, 2024). "In melanoma, YTHDF1 enhances lysosomal gene translation and protein expression thereby enhancing lysosome generation." (PMID 39661414, 2024). "We created a YTHDF1 deletion/inhibition prototype DC vaccine that significantly improved the therapeutic effect of RT and radioimmunotherapy in a murine melanoma model." (PMID 39325547, 2024). "Ythdf1-knockout mice showed an elevated anti-tumor response against melanoma xenografts due to increased antigen cross-presentation of YTHDF1-depleted dendritic cells." (PMID 37612540, 2023). "YTHDF1 is amplified in melanoma, and the combination of YTHDF1 and HNRNPA2B1 significantly increases the diagnostic validity." (PMID 36999016, 2023). "The m6A “reader” YTHDF1 modulates melanoma immune responses by enhancing antigen‐specific CD8+ T cell antitumor responses." (PMID 38089085, 2022). "Knockout of YTHDF-1 or blocking methylation of lysosomal protein RNA in DC inhibits tumor immune escape in melanoma patients." (PMID 33777035, 2021). "IHC results for YTHDF1 from 31 MCC patients revealed this protein to be expressed at high levels in 23/31 (74.2%) of samples while only 1/26 (3.8%) of melanoma patients expressed YTHDF1 at high levels." (PMID 31947544, 2020). "We also observed major mutations in YTHDF1 and HNRNPA2B1 that led to their amplification in melanoma." (PMID 32549786, 2020). "YTHDF1 deletion in mice showed slower growth of melanoma and higher survival rate compared to WT YTHDF1 by enhancing antigen specific CD8+ T cell antitumor response." (PMID 33718113, 2020). "We found that YTHDF1 was predominantly upregulated in brain and CNS cancer (n = 20), leukemia (n = 30), and melanoma (n = 10) datasets." (PMID 33317545, 2020). "To fully explore the role of YTHDF1 or HNRNPA2B1, we assessed their mutations using the cBioPortal Tool and found the two genes were mainly amplified in melanoma." (PMID 32549786, 2020). "Moreover, the control rate of melanoma by immunotherapy in YTHDF1 knockout mice increased to nearly 100%, while the rate was only 40% in WT mice." (PMID 37124930, 2023). "Finally, the study found that upregulating mutations in YTHDF1 and HNRNPA2B1 correlated with tumor stage and treatment response in patients, further supporting their roles, asm6A regulatory genes, in melanoma." (PMID 34105069, 2021). "In melanoma, the deletion of YTHDF-1 enhances the anti-tumor immune response." (PMID 33777035, 2021). "However, in melanoma, YTHDF1 might function as a tumor suppressor by facilitating the translation of the tumor suppressor gene histidine triad nucleotide-binding protein 2, thereby inhibiting tumor evolution." (PMID 38255219, 2024). "However, in melanoma YTHDF1 may act as a tumor suppressor that can promote the translation of the tumor suppressor gene histidine triad nucleotide binding protein 2 to inhibit tumor development." (PMID 36581942, 2022).